KRAS (KRas proto-oncogene, GTPase)
Diseases named in the same sentence as KRAS in open-access papers (continued):
Sharing a sentence is not in itself a finding about the gene and the disease.
gastric cancer (184 papers, 2005 to 2025). A primary or metastatic malignant neoplasm involving the stomach. "KRAS mutations occur in approximately 10%–15% of human gastric cancers, predominantly in the intestinal-type and microsatellite-unstable subtypes, making these models directly relevant to a significant subset of human disease." (PMID 40673273, 2025). "The predominance of tumor-associated macrophages in KRAS-driven lesions reflects the immunosuppressive microenvironment characteristic of human gastric cancers with mitogen-activated protein kinase pathway activation." (PMID 40673273, 2025). "KRAS mutations serve as key oncogenic drivers in many cancers by activating proliferative and immune-modulatory pathways, but are uncommon in gastric cancer, particularly in HP-negative cases." (PMID 40538856, 2025). "Some set of genes associated with the progression of gastric cancer such as KRAS signaling and Protein secretion were up-regulated especially in cluster C3." (PMID 40677704, 2025). "This limitation reflects a key difference from human KRAS-mutated gastric cancers, which typically demonstrate invasive behavior and metastatic potential, suggesting that additional oncogenic events are required for full malignant transformation." (PMID 40673273, 2025). "The G12V mutation is the common KRAS alteration in human gastric cancer, typically occurring in early stages of tumorigenesis and associated with enhanced proliferation and resistance to apoptosis." (PMID 40673273, 2025). "COX-2 upregulation is a consistent finding in human KRAS-mutated gastric cancers and represents a potential therapeutic target for prevention." (PMID 40673273, 2025). "This inflammatory signature mirrors the tumor microenvironment of human KRAS-mutated gastric cancers, which often exhibit elevated interleukin-6 signaling and enhanced C-X-C motif chemokine ligand 1-mediated neutrophil recruitment." (PMID 40673273, 2025). "KRAS mutations, which are among the most frequently observed genetic alterations in colorectal and gastric cancers, are consistently found in tumor samples." (PMID 39673361, 2024). "Dysregulational EGFR, KRAS, and mTOR pathways cause metabolic reprogramming, leading to progression of gastric cancer." (PMID 36145507, 2022). "Combined with somatic hotspot mutations, ERBB2 was activated in 9 of the 90 gastric cancers (10%), KRAS was in 6 (7%), and PIK3CA was in 4 (4%)." (PMID 34873204, 2021). "Our study suggests that CCNA2 is a novel biomarker predictive of sensitivity to PLK1 inhibitors for the treatment of advanced gastric cancer, particularly cases carrying KRAS mutation." (PMID 32486290, 2020). "We performed pharmacogenomics analysis using a gastric cancer cell line panel and discovered a causal linkage cascade of oncogenic KRAS mutation, aberrant CCNA2 upregulation and hypersensitivity to PLK1 inhibitors." (PMID 32486290, 2020). "The data suggest that H. pylori infection when compared with the absence of H. pylori infection, is associated with a higher prevalence of KRAS mutation in gastric cancer." (PMID 31217933, 2019). "The data of the present article demonstrated a significant association between H. pylori infection and KRAS gene mutation in gastric cancer patients." (PMID 31217933, 2019). "The aim of the current study was to assess the association of gastric cancer and KRAS mutation, demographic factors, and H. pylori infection." (PMID 31217933, 2019). "In agreement with previous studies, the current study observed an association between KRAS gene mutation and H. pylori infection in gastric cancer patients." (PMID 31217933, 2019).
gastric cancer (continued). "Considering genetic changes in cancers and the promise of cancer gene therapy, the current study assessed the mutation status of the KRAS gene in gastric cancer." (PMID 31217933, 2019). "In this study, we analyzed 140 FFPE samples of gastric cancer tissues for KRAS mutation and to detect H. pylori infection." (PMID 31217933, 2019). "The Cancer Genome Atlas Research Network and the Asian Cancer Research Group found activating mutations in KRAS to be present in gastric cancer tumors, particularly in 25% of microsatellite-instable (MSI) subtypes of gastric cancer." (PMID 30597917, 2018). "This study provides more data support for clinical research on KRAS/NRAS/BRAF mutation in CRCs or gastric cancers." (PMID 30416987, 2018). "In a previous study, we associated the cetuximab resistance of the gastric cancer cell line AGS with an activating KRAS mutation." (PMID 27933395, 2017). "Taken together, our studies indicate that KRAS amplifications and KRAS mutations are of less importance for predicting cetuximab sensitivity in gastric cancer, especially regarding cell migration." (PMID 29237412, 2017). "We previously demonstrated that activation of MET and mutations in KRAS or CDH1 were linked to the cetuximab insensitivity in gastric cancer cell lines." (PMID 29237412, 2017). "The authors also analyzed the somatic mutations of EGFR, ERBB2, PIK3CA, KRAS, and BRAF genes in these 12 samples harboring ERBB4 mutations and detected a KRAS mutation in 1 gastric cancer sample." (PMID 29371993, 2017). "Previous data also showed that CTNNB1 (1–9 %) and KRAS (5–6 %) mutations were relatively uncommon in gastric cancer." (PMID 27782820, 2016). "miR-127 has been shown to exert tumor suppressive functions in gastric cancers by interacting directly with the mRNA-encoding oncogenic factors KRAS and MAPK4." (PMID 27775664, 2016). "EGFR is expressed in epithelial cells of gastric cancer at a relatively high level, and the mutation rate of KRAS in gastric cancer is much lower than that in colorectal cancer (4.2%), and therefore EGFR-targeted therapy is the present research hot spot." (PMID 26880889, 2016). "Direct sequencing of gastric cancer specimens revealed the proportion of KRAS, BRAF, and PIK3CA mutations." (PMID 26207151, 2015). "The reciprocal relationship between KRAS mutation and copy number alterations is also observed in gastric cancer." (PMID 23078675, 2012). "In aggregate, we found that PI3K inhibition by NVP-BKM120 cooperated with AG490 in gastric cancer cells harboring mutated KRAS." (PMID 22159814, 2012). "We used median-effect analysis of dose-response curves to calculate the CI values and the results were represented as synergy in KRAS-mutated gastric cancer cell lines, SNU-1, SNU-601 and SNU-668." (PMID 22159814, 2012). "Although colorectal tumours with an activating mutation of the Kirsten(K)-ras gene are not sensitive to EGFR antibodies, the incidence of KRAS mutations in gastric cancer appears to be low." (PMID 20068568, 2010). "Aberrant activation of KRAS is a key factor in the development of many types of tumor, however, oncogenic mutations of KRAS are infrequent in gastric cancer." (PMID 19545448, 2009). "Future studies using a larger cohort of gastric cancer specimens are needed to elucidate the clinical, diagnostic and therapeutic significance of KRAS amplification and overexpression." (PMID 19545448, 2009). "Additional studies using a larger cohort of gastric cancer specimens are required to determine the diagnostic and therapeutic implications of KRAS amplification and overexpression." (PMID 19545448, 2009).
gastric cancer (continued). "This discrepancy highlights the importance of cellular context and genetic background in determining oncogene effects, reflecting the heterogeneity observed in human KRAS-mutated gastric cancers where additional cooperating mutations determine clinical behavior." (PMID 40673273, 2025). "BRAF V600E mutations occur in approximately 2%–5% of human gastric cancers and are associated with microsatellite instability and better response to immunotherapy, making this comparison between KRAS and BRAF particularly relevant for understanding pathway-specific effects." (PMID 40673273, 2025). "Consequently, evaluation of the KRAS mutational status is essential to guide treatment strategies for both colorectal and gastric cancer management." (PMID 39673361, 2024). "Additionally, it is worth noting that KRAS mutations have also been established in gastric cancer, and alterations in the RAS pathway, caused by both RAS and BRAF mutations, play a role in the pathogenesis of gastric cancer." (PMID 39673361, 2024). "Interestingly, the interrogation of gastric cancer databases showed that the co-occurrence of KRAS and PIK3CA pathway mutations is around twofold more frequent for A146T than for the other mutants (66% vs 23%, Suppl." (PMID 38261067, 2024). "However, KRAS is targeted by deleterious mutations in multiple gastric carcinoma subtypes including EBVaGC2." (PMID 38746323, 2024). "SB-PCCs may harbor RHOA mutations, which are reminiscent of the diffuse subtype of gastric cancers or appendiceal GCAs, while KRAS and PIK3CA mutations, commonly involved in colorectal and small bowel adenocarcinomas, are not typical of such cancers." (PMID 36812376, 2023). "Similarly, KRAS mutations are rare in intestinal-type and diffuse/poorly cohesive gastric carcinomas (<10% of cases), appendiceal GCAs (0%-6%), and SRC adenocarcinomas (0%).35,42-44 Interestingly, Jun et al45 found no KRAS mutations in four SRC SBAs." (PMID 36812376, 2023). "Similarly, KRAS mutation frequency is also very low in advanced gastric cancer (4.9%), even in a report showing a comparatively high frequency." (PMID 34884530, 2021). "KRAS mutation was detected in 6 of the 140 (4.2%) gastric cancer tissue samples." (PMID 31217933, 2019). "In spite of much research, the clinicopathologic significance of KRAS mutation in gastric cancer remains unknown." (PMID 31217933, 2019). "In 1986, for the first time, a mutation in the KRAS gene of a gastric cancer patient was reported." (PMID 31217933, 2019). "There are few studies on the mutations rate of KRAS/NRAS/BRAF in gastric cancer." (PMID 30416987, 2018). "A pan-HER inhibitor, PF0029984, was tested in seven gastric cancer cell lines, each having one of the following abnormalities: KRAS mutation; amplification of FGFR2, MYC (V-Myc avian myelocytomatosis viral oncogene homolog) or MET (MET proto-oncogene receptor tyrosine kinase)." (PMID 29872697, 2017). "KRAS is mutated in a significant proportion but BRAF is mutated less frequently in gastric cancers." (PMID 27437872, 2016). "In gastric carcinomas, the reported frequency of KRAS point mutations is between 8% and 10%." (PMID 24454858, 2014).
gastric cancer (continued). "Downstream of the RTKs, KRAS wildtype amplification and mutation has also been found in about 9-15% of gastric cancers and may be effectively treated with MEK inhibitors." (PMID 21781349, 2011). "Moreover, one recently described mechanism of resistance against cetuximab, that is the activating mutation of the KRAS gene, seems to have a very low prevalence in gastric cancer." (PMID 20068568, 2010). "While gain-of-function mutations of KRAS are some of the most commonly observed genetic alterations in a variety of tumors, including pancreatic (60%), biliary tract (33%) and colon (32%), these mutations are infrequent in gastric cancer (2–7%)." (PMID 19545448, 2009). "Moreover, though the overall incidence of KRAS mutation in the studied population was low (8 in 94), 2 of the 4 gastric cancers with PIK3CA mutation also harboured a KRAS mutation." (PMID 15784156, 2005). "Guo and his colleagues showed that the ectopic expression of miR-433 and miR-127 in gastric cancer cell lines inhibits cell proliferation, cell cycle progression, cell migration, and invasion by directly interacting with the mRNA encoding oncogenic factors KRas and MAPK4, respectively." (PMID 25477702, 2014). "Finally, a codon 12 mutation in the KRAS gene was identified, equivalent to those found in human gastric carcinomas, suggesting that this altered pathway may also exert a role in the pathogenesis of gastric cancer in dogs." (PMID 24454858, 2014). "The combination of KRAS activation and APC loss recapitulates the cooperative effects observed in human gastric cancers with both alterations, which typically show more aggressive behavior." (PMID 40673273, 2025). "KRAS WT amplification in gastric cancers augments the level of KRAS WT “ON” and increases downstream oncogenic signaling." (PMID 39711431, 2025). "Pathogenic missense mutations in MUC5AC, KRAS, BRAF and EZH2 exhibited significant overlap between SPEM and intestinal-type gastric cancer." (PMID 41195276, 2025). "TLR4 and KRAS, as common genes for immune infiltration and ferroptosis, are involved in gastric carcinogenesis and play an important role in gastric cancer progression." (PMID 36936437, 2023). "The two gastric carcinoma cases showed an ERBB2 R678Q pathogenic variant with a PIK3CA E542K and KRAS G12V variants." (PMID 36125633, 2023). "Our study also found many patients with clonal pathogenic mutations in the RAS/RAF pathway gene KRAS and the PI3K/MTOR/AKT pathway gene PIK3CA, providing further evidence of their importance in gastric cancer biology." (PMID 36970058, 2022). "The KRAS signaling pathway promotes metastasis and chemotherapy resistance of cancer stem cells in stomach cancer." (PMID 35712475, 2022). "A study of gastric cancer patients detected a high frequency of mutations in MLL4, ERBB3, FBXW7, MLL3, mtor(RPTOR), NOTCH1, PIK3CA, KRAS, ERBB4 and EGFR." (PMID 33909629, 2021). "ERBB2 was most frequently amplified (6 of the 90 gastric cancers, 7%), and KRAS (2 cancers, 2%), PIK3CA (1 cancer, 1%), and MET (1 cancer, 1%) followed." (PMID 34873204, 2021). "5, 5, 3, and 2 mutations of KRAS, PIK3CA, ERBB2 and CTNNB1 were observed in 4, 4, 3, and 2 gastric cancers, respectively (5, 3, 3, and 2 hotspot mutations, respectively)." (PMID 34873204, 2021). "We found that KRAS‐amplified gastric cancer cells showed overexpression of KRAS protein, possessing a large pool of inactive KRAS (KRAS‐GDP state)." (PMID 33532680, 2021).
gastric cancer (continued). "Like in gastric cancer, EAC, and CRC patients, KRAS amplification is associated with worse survival in ESCC patients." (PMID 34285259, 2021). "Other genes that were commonly mutated in AN gastric cancer patients were PIK3CA, PTEN, KRAS, APC, and CTNN1B, which were comparable to the TCGA study." (PMID 31941061, 2020). "Further, we demonstrated that CCNA2 expression is elevated in KRAS mutant gastric cancer cell lines and primary tumors, resulting in an increased sensitivity to PLK1 inhibitors." (PMID 32486290, 2020). "While activating KRAS mutations are well characterized in various carcinomas, there is little reliable data on the relevance of KRAS amplification in gastric carcinoma." (PMID 32571252, 2020). "In summary, we present the importance of KRAS amplification in gastric carcinoma in a large cohort of 582 Caucasian patients." (PMID 32571252, 2020). "This work demonstrates the relevance of the heterogeneity of KRAS amplified tumor clones in gastric carcinoma for the first time." (PMID 32571252, 2020). "Our data have afforded the conclusion that a novel therapeutic strategy against HER2-positive gastric cancer would be the perturbation of KRAS networks by tumor suppressor miR-143." (PMID 30959742, 2019). "The closest example reported so far is a synergism between inhibition of pan class I PI3K and STAT3 in KRAS mutant-driven gastric cancer cells." (PMID 30755611, 2019). "To examine the effect of silencing KRAS in HER2-positive gastric cancer cell lines, we performed a cell viability assay and Western blotting after the transfection of MKN-7 and KATO-III cells with siR-KRAS." (PMID 30959742, 2019). "Our data indicated a novel therapeutic strategy against HER2-positive gastric cancer involving perturbation of KRAS networks including the DDX6 mediated by tumor suppressor miR-143." (PMID 30959742, 2019). "In the HER2/KRAS cascade, the expression level of KRAS was up-regulated in HER2-positive gastric cancer cell lines MKN-7 and KATO-III compared with that in the other cell lines." (PMID 30959742, 2019). "KRAS G12D (ACC > ATC) and KRAS G13D (GCC > GTC) were associated with MMR signatures in uterine carcinoma and stomach cancer, respectively." (PMID 29748584, 2018). "For two of the gastric cancer cell lines analyzed in this study, genetic defects concerning KRAS have been published." (PMID 29237412, 2017). "The aim of this study was to investigate the clinicopathologic and genomic status, especially KRAS status, of gastric cancer (GC) patients according to MEK signature in two Asian cohorts using clinical samples." (PMID 29296181, 2017). "For instance, the level of miR-433 is decreased in human gastric carcinoma, which is associated with unfavorable outcome in overall survival, and GRB2 and KRAS are direct target of miR-433 in human gastric carcinoma." (PMID 27926502, 2017). "PRKAA1 amplification and genetic alteration occur simultaneously along with other oncogenes, such as KRAS, in various solid tumors including gastric cancer." (PMID 27726301, 2016). "Proliferation of KRAS-G12D-mutant SNU-1 gastric cancer cells was abrogated by knockdown of the type I IGF receptor and reduced by its pharmacological inhibition." (PMID 27437872, 2016). "A recent genomic study of gastric cancers identified somatic copy number alterations of seven oncogenes involved in tyrosine kinase/MAP-kinase pathways: KRAS, EGFR, HER2, FGFR1, FGFR2, MET and IGF1R." (PMID 27437872, 2016). "Receptor tyrosine kinase (RTK)-related genes, including HER2, EGFR, MET, FGFR2 and KRAS, are target molecules that are clinically beneficial in gastric cancer (GC)." (PMID 27014419, 2016).